GSDMB (gasdermin B)
Diseases named in the same sentence as GSDMB in open-access papers (continued):
Sharing a sentence is not in itself a finding about the gene and the disease.
tumor (continued). "The promoter methylation level of GSDMB negatively regulated the degree of tumor development and tumor differentiation of KIRC." (PMID 37064151, 2023). "The role and function of GSDMB in the tumor are being widely studied, and its increased expression is related to immune infiltration and poor prognosis." (PMID 37324016, 2023). "In tumors, GSDMB promotes either pro-tumor or anti-tumor functions depending on the biological context." (PMID 36899106, 2023). "Granzyme A can induce pyroptotic death against tumor cells with gasdermin B protein, which is expressed abundantly in epithelial cells in the gastrointestinal tract." (PMID 36769513, 2023). "Recently, GSDMB has been demonstrated to be cleaved by granzyme A from cytotoxic lymphocytes to induce pyroptosis in GSDMB-expressing tumor cells." (PMID 37705753, 2023). "The results showed tumours with high expression of GSDMB and caspase-6 to be mainly immune inflammatory tumours, with those having poor expression of GSDMB and caspase-6 being mostly immune-desert tumours." (PMID 36702978, 2023). "This suggests that the synergy between GSDMB expression and anti-PD-1 therapy holds promise for impeding tumor progression." (PMID 38066523, 2023). "Further analysis of the relationship between the BLCA tumor stage and GSDMB expression showed that the expression of GSDMB was inhibited in advanced BLCA tumors (p = 0.00123), which is consistent with the clinical prognostic data." (PMID 37064151, 2023). "GSDMB is highly expressed in tumor cells and is able to destroy them by triggering pyroptosis, lysing cells with GZMA, and releasing active pore-forming fragments." (PMID 37705746, 2023). "Mechanistically, IBI315 triggers gasdermin B (GSDMB)‐mediated pyroptosis in tumor cells, leading to the activation and recruiments of T cells." (PMID 37587833, 2023). "Granzyme A induces pyroptosis by hydrolyzing GSDMB, which results in tumor cell death, indicating that pyroptosis positively affects the tumor immune response process." (PMID 35311148, 2022). "Once again, while lapatinib alone mainly decreased tumor weight and volume in GSDMB-silenced tumors, the addition of CQ enhanced the effect of lapatinib on the reduction of tumor growth exclusively in GSDMB-expressing (shNTC) tumors." (PMID 36163066, 2022). "GSDMB and GSDME, which have been reported to be associated with anti-tumor immunity in human cancer." (PMID 36068291, 2022). "Next, to validate if the combination of lapatinib and CQ on HER2/GSDMB positive tumors would be an effective therapeutic approach, we assayed its functional effect on tumor growth in vivo using two different preclinical models, zebrafish, and mice." (PMID 36163066, 2022). "Recently, it has been revealed that lymphocyte-derived Granzyme-A can cleave GSDMB within tumor cells, thus provoking a pyroptotic cancer cell death." (PMID 36163066, 2022). "In separate research published the same year, CD8+ T cells and NK cells were demonstrated to promote tumor clearance via the GSDMB granzyme A axis." (PMID 35085103, 2022). "GZMA from the NK cell and CTLs were proven to induce pyroptosis in murine tumor cells via the cleavage of GSDMB, which not only enhances the antitumor immunity but also promotes tumor clearance." (PMID 36119049, 2022). "In a co-culture system, cytotoxic lymphocytes induced pyroptosis in tumor cells and the killing effects resulted from the cleavage of GSDMB by lymphocyte-derived granzyme A." (PMID 36077828, 2022). "Both granzyme A and B-mediated cleavage of gasdermin B and E, respectively, have been shown to contribute to tumour control by cytotoxic lymphocytes." (PMID 35401556, 2022). "This study demonstrates that activation of GSDMB induces pyroptosis and promotes tumor clearance, supporting an important regulation of reactivation in our predicted formula with a high-risk factor." (PMID 35669428, 2022).
tumor (continued). "When granzymes were delivered directly to tumor cells during a cytotoxic T cell attack, GSDMB and GSDME were cleaved into N- and C- terminal fragments by GZmA and GZmB, respectively." (PMID 36159393, 2022). "Granzyme A, which is released by CTLs and natural killer cells, can directly cleave GSDMB to mediate tumor cell pyroptosis." (PMID 35928454, 2022). "Remarkably, consistent with GSDMB tumor suppressor function, Zhou and colleagues report a frequent GSDMB downregulation in gastroesophageal carcinomas, which contradicts previous studies in these tumors." (PMID 35281099, 2022). "Pyroptosis induced by GSDMB will enhance anti-tumor immunity and become a potential target for the treatment of these tumors." (PMID 36497244, 2022). "For instance, CD8+ T cells and NK cells in the TME can trigger tumor clearance via the GSDMB granzyme A axis, which is aided by IFN-γ." (PMID 36152052, 2022). "GZMA cleaves and activates GSDMB NT in cancer cells subsequently producing tumor pyroptosis and cancer regression." (PMID 35281099, 2022). "For example, cytotoxic T lymphocytes and NK cells express and release granzyme A into targeted tumor cells to cleave and activate GSDMB, leading to tumor cell pyroptosis." (PMID 36077828, 2022). "Paradoxically, GSDMB can also have tumor suppressor (cell death induction) effects in specific biological contexts." (PMID 35281099, 2022). "In murine tumours, gasdermin B expression synergised with checkpoint blockade to promote tumour clearance by cytotoxic lymphocytes." (PMID 35401556, 2022). "Granzyme A from cytotoxic T-cells cleaves GSDMB in the tumour cells at lysine 229 and 244 leading to pore formation in target cells." (PMID 35626754, 2022). "Whereas both approaches yielded promising results, only partial tumor regression was achieved, and so far, it is still unproven if GSDMB-mediated pyroptosis actually occurs in clinical tumor samples." (PMID 36163066, 2022). "In these models we performed the first comprehensive in vivo study of GSDMB effects on tumor initiation and development." (PMID 35281099, 2022). "A study published in 2020 discovered that CD8+ T cells and natural killer (NK) cells boosted tumor clearance via the GSDMB–granzyme A axis." (PMID 35677632, 2022). "The analysis demonstrated that in comparison with normal brain tissues, 20 pyroptosis-related genes were upregulated in the tumor (e.g. CASP1 and CASP3), and 11 pyroptosis-related genes were significantly downregulated in the tumor (e.g. GSDMB and NLRP1)." (PMID 35274175, 2022). "Our novel models are useful to identify the precise stimuli and molecular mechanisms governing GSDMB functions in neoplasias and can be the basis for the future development of additional tissue-specific and context-dependent cancer models." (PMID 35281099, 2022). "Accordingly, the combination of lapatinib with the autophagy inhibitor chloroquine increases the therapeutic response of GSDMB-positive cancers in vitro and in zebrafish and mice tumor xenograft in vivo models." (PMID 36163066, 2022). "Meanwhile, the overexpression of GSDMB in cancer cells leads to the recruitment of immune cells and promotes tumor mobility and invasion." (PMID 36003332, 2022). "GSDMB was found to exert pro-tumor function by promoting proliferation, migration and invasion of tumor cells in both breast neoplasias and bladder cancer." (PMID 36505474, 2022). "GSDMB has tissue-specific expression and is highly expressed in tumor cells originated from epithelial cells of the digestive system." (PMID 36497244, 2022). "Partial inhibition of tumor growth was also seen in CT26 tumors expressing the GzmA-resistant double mutant form of GSDMB under the PD-1 antibody condition, but only to an extent near that of control tumors." (PMID 34429144, 2021). "When it becomes activated, GSDMB mediates pores formation in tumour cells which are ultimately swollen and destroyed." (PMID 33815694, 2021).
tumor (continued). "The Human Protein Atlas and the Clinical Proteomic Tumor Analysis Consortium (CPTAC) were used to assess the protein expression of GSDMB." (PMID 34957313, 2021). "Introducing GZMA-cleavable GSDMB into colon carcinoma and melanoma cells almost completely restrained tumor growth in mice." (PMID 33634141, 2021). "Analogously, Zhou et al37 showed that GzmA, which is also derived from cytotoxic T cells and NK cells, can enhance tumour clearance via directly triggering GSDMB‐mediated cancer cell pyroptosis." (PMID 34590363, 2021). "GSDMB is highly expressed in tumor cells derived from epithelial cells of the digestive system and GSDMB-mediated pyroptosis can enhance the antitumor immunity." (PMID 34381721, 2021). "It consists of a necrotic cell death conveyed by the activation of gasdermin‐B (GSDMB) on the surface of the tumour cell." (PMID 33815694, 2021). "The potential relation between the expression of GSDMB and the six different types of tumor-infiltrating immune cells was analyzed via the TIMER database." (PMID 34957313, 2021). "Next, the analysis of three independent cohorts (totalizing 286 tumours) showed that approximately 65% of the HER2-positive cases have GSDMB gene amplification and protein over-expression." (PMID 27462779, 2016). "As expected, 61.1% and 68.8% of the HER2-positive tumours showed GSDMB amplification and protein expression, respectively; in fact, a strong association between both variables was observed (p < 0.001)." (PMID 27462779, 2016). "In the six cases classified as HER2-negative tumours showing GSDMB amplification, the HER2/centromere ratio was 1.9 + 0.24, suggesting the presence of HER2 aneuploidy." (PMID 27462779, 2016). "Using copy number estimates from The Cancer Genome Atlas (TCGA) dataset, the GSDMB locus was shown to be amplified in 58 out of 526 (11%) tumours." (PMID 27462779, 2016). "At the same time, if the pore-forming pyroptotic function of GSDMB is activated in cancer cells, it may also have anti-tumor effects, which can be triggered in vitro by granzyme A (GZMA) cleavage." (PMID 40452932, 2025). "Moreover, the sensitivity of tumor cells to granzyme A‐mediated pyroptosis is determined by AS of GSDMB." (PMID 41399527, 2025). "Moreover, inflammation has been shown to further enhance GSDMB expression in tumors, creating a positive feedback loop that can promote tumor cell death." (PMID 40783818, 2025). "Notably, this process is reinforced by a positive feedback loop, as IFN-α and TNF-γ produced by cytotoxic lymphocytes upregulate GSDMB expression in target cells, enhancing tumor clearance in murine models." (PMID 40200299, 2025). "Moreover, GSDMB’s role in modulating immune responses and its interactions within the tumor microenvironment position it as a promising therapeutic target." (PMID 40452932, 2025). "While the function of GSDMB in anti-tumor immunity through pyroptosis is well characterized, GSDMB was also reported to have pyroptosis-independent function such as its regulation of PDGF-A-mediated FAK phosphorylation, MAVS-TBK1 signaling and 5-lipoxygenase (5-LO)-mediated TGF-β1 expression." (PMID 38737375, 2024). "However, translating this potential into clinical practice requires careful investigation and understanding of the interaction of GSDMB-induced pyroptosis with various types of immune cells to ensure specificity for tumor cells and to avoid off-target effects." (PMID 38304430, 2024). "Spatial transcriptomics and mIHC analysis revealed that CD8+TILs co-expressing GZMA and IFN-γ may localize near GSDMB-expressing tumor cells, suggesting potential interactions between these cell types." (PMID 39030523, 2024). "Generally, GSDMB exhibits a dual effect of promoting and inhibiting tumor progression." (PMID 38304430, 2024). "Positive nuclear GSDMB expression indicated more CD68+ macrophages in the tumor microenvironment." (PMID 38711020, 2024).
tumor (continued). "In addition, mice inoculated with CT26 containing high GSDMB expression displayed a complete tumor regression after anti PD‐1 treatment, indicating the important role of GSDMB in regulating tumor cell death." (PMID 37984863, 2024). "Notably, the presence of IFN‐γ in TME can promote the expression of GSDMB in tumour cells and the GZMA‐GSDMB axis efficacy." (PMID 38652105, 2024). "In addition to GZMB, another serine protease derived from cytotoxic lymphocytes, granzyme A(GZMA), can segment GSDMB and induce pyroptosis in tumor cells." (PMID 38304430, 2024). "However, when GSDMB expression was combined with anti-PD-1 therapy, significant inhibition of tumor growth was observed in CT26 cells." (PMID 38066523, 2023). "Conversely, the pre-cancer and cancerous samples show moderate or augmented GSDMB expression, suggesting that the rich content of GSDMB may be related to tumor invasion." (PMID 38016064, 2023). "Cytotoxic lymphocyte-derived granzyme A is able to cleave GSDMB and induce tumor cell pyroptosis." (PMID 37635159, 2023). "A second major function of GSDMB is to facilitate tumor clearance in anti-tumor immunity." (PMID 36599845, 2023). "Therefore, triggering GSDMB pyroptotis has been proposed as a promising approach for efficient tumor killing." (PMID 36899106, 2023). "Kyoto Encyclopedia of Genes and Genomes (KEGG) and Gene Ontology (GO) enrichment analyses showed that GSDMB and its interacting proteins might affect tumor growth through the serine metabolism pathway." (PMID 37064151, 2023). "Based on these observations, we hypothesized that IBI315‐induced pyroptosis in tumor cells may occur through the mediation of granzyme A secretion by cytotoxic lymphocytes, contributing to the cleavage of GSDMB." (PMID 37587833, 2023). "Besides the activation through the canonical and apoptotic pathways, lymphocyte-derived granzyme A cleaved GSDMB in human epithelial cells and led to a significant tumor clearance in co-treatment with an anti-PD-1-antibody in a murine tumor model." (PMID 37664463, 2023). "This highlights the potential of GSDMB as a promising target for tumor treatment." (PMID 38066523, 2023). "Based on biological process (BP) analysis, GSDMB may participate in immune response, programmed cell death, biosynthetic process, and other pathways to regulate tumor progression." (PMID 37064151, 2023). "The enzyme‐linked immunosorbent assay (ELISA) analysis of coculture supernatants found that after the knockdown of GSDMB in tumor cells, the addition of IBI315 no longer caused the elevation of IL‐18 in the coculture supernatants." (PMID 37587833, 2023). "Notably, we did not observe any difference in the frequency of CNV gains or losses in NRGs between tumor and normal samples, except for GSDMB, which exhibited a downregulation of mRNA expression." (PMID 37989855, 2023). "In addition, GSDMB is expressed in a variety of tumor cells and is closely related to the occurrence and development of these tumors, skin cutaneous melanoma, and bladder carcinoma." (PMID 37125240, 2023). "CTLs can induce pyroptosis in human GSDME or GSDMB-sensitized tumor cells." (PMID 37705746, 2023). "Notably, the activated T cells secrete Interferon‐gamma (IFNγ), which in turn enhances GSDMB expression, thus establishing a positive feedback loop that augments T cell activation and facilitates efficient tumor cell elimination." (PMID 37587833, 2023). "CD8+ T cells and NK cells released granzymes that could cleave GSDMB/E and thus triggered tumor cell pyroptosis, indicating that pyroptosis might play a role in anti-tumor immunity." (PMID 36152052, 2022). "Using AsPC-1 cells in which GSDME was knocked out, we further demonstrated that only WT GSDME (not GSDME-D270A or WT GSDMB) rescued the GSDME-deficiency-retarded tumour growth in the pancreas." (PMID 35292781, 2022).
tumor (continued). "Moreover, GZMA-derived natural killer cells and CTLs can directly cleave GSDMB and trigger pyroptosis in cancer cells, leading to tumor clearance in a mouse model." (PMID 35990696, 2022). "Furthermore, pyroptosis-induced anti-tumor immunity should also be considered as GSDMB has been shown to dramatically improve anti-tumor effects of anti PD-1 therapy." (PMID 36077828, 2022). "In addition, CD8 + T cells and NK cells also induce tumour cell pyroptosis through the granzyme-A/GSDMB axis." (PMID 35896522, 2022). "Likewise, contrary to its pro-tumor effects, GSDMB can have tumor suppressor function in certain conditions." (PMID 35281099, 2022). "Higher mRNA expression levels of GSDMB/D/E were related to higher tumor stage." (PMID 35321945, 2022). "Remarkably, autophagy blockage by CQ provoked an increase in the effect of lapatinib on tumor growth reduction (p < 0.001) only in GSDMB-expressing (shNTC) tumors, compared to lapatinib alone, while no such effect was observed in GSDMB-silenced (shGB1, shGB2) tumors." (PMID 36163066, 2022). "In addition, the expression of GSDMB in tumor cells increased and promoted the growth, invasion, metastasis of neoplasm." (PMID 35647057, 2022). "In this sense, an activated anti-tumor immune response mediated by NK and T-cytotoxic cells could reduce tumor growth of murine colon and melanoma cells exogenously overexpressing GSDMB." (PMID 36163066, 2022). "GSDMB is also involved in pyroptosis, it can promote atypical pyroptosis by enhancing the activity of caspase-4 and has the function of inhibiting the proliferation of tumor cells." (PMID 35571063, 2022). "Subsequently, another study showed that granzyme A released from cytotoxic NK and T lymphocytes could cleave GSDMB, thereby triggering the prolapse of target cells and leading to tumor clearance." (PMID 36068291, 2022). "PD-1 antibody treatment exclusively promotes the clearance of GSDMB+ tumour grafts." (PMID 35896522, 2022). "Two recent studies found that granzymes released by CD8+ T cells and NK cells can cleave GSDMB/E, thereby triggering tumor cell pyroptosis, and pyroptosis may be an important effector in anti-tumor immunity." (PMID 36090967, 2022). "Similarly, NK cells and CD8+ T cells have been recently shown to trigger tumor clearance via the GSDMB-granzyme A axis, and higher enrichment of NK and CD8+ T cells usually reflects better ICB efficacy." (PMID 35784306, 2022). "In LIHC, correlation analysis of gasdermin family gene expression with tumor microenvironment revealed that GSDMA and GSDMC expressions were positively related to stromal score, whereas GSDMB and PJVK expressions were negatively associated with the stromal score." (PMID 35922531, 2022). "Some studies showed that GSDMB can promote pyroptotic death and inhibit the growth of tumor cells." (PMID 34326684, 2021). "High-level expression of GSDMB in cancer cells enhanced tumor clearance in a mouse model." (PMID 34179006, 2021). "The Tumor Immune Estimation Resource (TIMER) and tumor-immune system interaction database (TISIDB) were utilized to determine the association between the mRNA expression of GSDMB and immune infiltrates." (PMID 34957313, 2021). "Moreover, GSDMB expression is notably correlated with methylation status, and the signature is related to antitumor immunity in the tumor microenvironment." (PMID 34867395, 2021). "Specifically, intracellular delivery of the anti-GSDMB antibody by nanocapsules could inhibit tumor growth and metastasis in vivo." (PMID 33634141, 2021). "Two other recent studies found that the granzymes released from CD8 +T cells and NK cells could cleave GSDMB/E and thus trigger the pyroptosis of tumor cells, indicating that pyroptosis might serve as an important effector in anti-tumor immunity." (PMID 34298833, 2021). "It demonstrates that tumor immune escape might be involved in GSDMB-mediated carcinogenesis of ccRCC." (PMID 34957313, 2021).